CXCR4 (C-X-C motif chemokine receptor 4)
Diseases named in the same sentence as CXCR4 in open-access papers (continued):
Sharing a sentence is not in itself a finding about the gene and the disease.
Obesity (24 papers, 2012 to 2025). Accumulation of substantial excess body fat. "A study showed that CXCR4 deficiency in adipocytes exacerbates obesity and compromises the thermoregulatory responses of brown adipose tissue in a mouse model of diet-induced obesity." (PMID 40302245, 2025). "FOXM1 and CXCR4, as the most important key genes, were overexpressed in obesity and BC, and its overexpression was associated with high occurrence and worse outcome of BC." (PMID 35481418, 2022). "CXCR4 is a chemokine receptor expressed in adipocytes, macrophages and hepatic stellate cells that protects against obesity and obesity associated inflammation." (PMID 27902747, 2016). "Additionally, hypoxia, a condition that has been associated with both obesity and leptin, increases CXCR4 expression on monocytes and macrophages, thereby inducing TAM trafficking and retention into the low oxygen tension tumor areas." (PMID 32260113, 2020). "By inhibiting the excessive recruitment of inflammatory cells into the WAT and promoting the BAT’s thermogenic activity, adipocyte C-X-C motif chemokine receptor 4 (CXCR4) prevents the development of obesity." (PMID 38650945, 2024). "It has been also demonstrated that during obesity, CXCR4 is involved in macrophage recruitment to the adipose tissue." (PMID 32260113, 2020). "Obesity, insulin-dependent diabetes, and hypertension were associated with higher levels of the CD45–CD34 + CXCR4+ and the CD45–CD34 + CXCR7+ cells." (PMID 29744773, 2018). "Obesity and insulin-dependent diabetes were associated with higher levels of the CD45–CD34 + CXCR4+ cells." (PMID 29744773, 2018). "Importantly, the CXCR4-defeciency in adipocytes leads to exacerbated obesity and impairs the brown adipose tissue thermoregulatory process." (PMID 34944474, 2021). "In addition, we demonstrated associations of CXCR4 and HHEX with overweight/obesity (OR = 1.6, p = 0.003) and (OR = 1.4, p = 0.002), respectively, in 1333 sib-pairs (2666 individuals)." (PMID 23349771, 2013). "This correlated with our previous hypothesis in which TFF2 would be a signal aiming to limit the food intake and obesity development since CXCR4 deficiency would prevent TFF2 from playing the related metabolic roles in limiting obesity and thus, explains the exacerbated obesity." (PMID 34944474, 2021). "Primary examples include chemokine receptors (CXCR1, CXCR2, CXCR4, CCR5, CCR7) that drive chronic inflammatory responses common to both obesity and cancer." (PMID 33329395, 2020). "Our findings suggested that BBR ameliorates obesity-induced inflammation by regulating macrophage infiltration and polarization in AT, which resulted from the suppression of chemokine signaling pathways, including CCL2 and CXCR4." (PMID 35885044, 2022). "Sufficient archival formalin-fixed paraffin-embedded biopsy tissue was available to determine CXCR4 and SDF-1 expression in six samples from patients with biopsy-proven and clinically correlated obesity-related secondary FSGS compared with ten samples from time-zero live kidney donors." (PMID 24637920, 2014). "Additionally, mice lacking CXCR2 show resistance to the onset of obesity-induced disorders of glucose metabolism, and a recent study found that SDF-1/CXCL12, which is secreted from hypertrophic adipocytes, recruits macrophages via CXCR4, which is the receptor of SDF-1/CXCL12, during obesity." (PMID 26197341, 2015).
squamous cell carcinoma (24 papers, 2005 to 2025). A carcinoma arising from squamous epithelial cells. "Particularly striking were our findings for metastatic squamous cell cancers originating from a range of tissues, for which 15 of 17 cases were CXCR4+." (PMID 29088715, 2017). "CXCR4 was mostly expressed in squamous carcinoma tissues and localized mainly to the cytoplasm and partially to the cell membrane." (PMID 25866764, 2015). "All of the squamous cell carcinoma or adenocarcinoma lung tumor specimens examined expressed positive staining for CXCR4." (PMID 19563666, 2009). "A slightly higher expression of CXCR4 (94.1% in squamous cell carcinoma and 89.1% in adenocarcinoma of the esophagus) was found as compared to other studies." (PMID 17176471, 2006). "In patients with squamous cell carcinoma, a significant difference between the two groups of CXCR4 expression was found for tumor grading (p = 0.030)." (PMID 17176471, 2006). "In squamous cell carcinoma, patients with a weak CXCR4 expression had a mean survival of 25 (+/- 5 SD) months after surgery as compared to only 17 (+/- 4 SD) months in the group with strong chemokine expression." (PMID 17176471, 2006). "Of note, CXCR4 could provide an additional marker for metastatic tendency in adenocarcinoma or squamous cell carcinoma." (PMID 33579381, 2021). "It was also noteworthy that out of the 17 metastatic squamous cell cancers whose sites of origin included colon (1 of 17), esophagus, larynx, lung, nasopharynx, penis, and unknown tissues, 15 were CXCR4+." (PMID 29088715, 2017). "The respective overall expression rate for CXCR4 in squamous cell carcinoma was 94.1%." (PMID 17176471, 2006). "Another anti-CXCR4 treatment, TN14003, has been shown to suppress primary tumor growth by inhibiting tumor angiogenesis and preventing lung metastasis of squamous cell carcinoma of the head and neck in animal models." (PMID 24137439, 2013). "To examine if CXCR4 expression is influenced by the differentiation status in NPC, we collected 26 NPC samples consisting of 6 keratinising squamous cell carcinomas, 10 differentiated carcinomas and 10 undifferentiated carcinomas." (PMID 15978137, 2005). "Expression profiling of CXCR4 transcript was done by semiquantitative RT-PCR in eight CC cell lines (HeLa, SiHa, ME-180, C-33A, CaSki, C-4I, MS751, and SW756), 63 (60 squamous cell carcinomas and 3 adenosquamous) primary tumor biopsies, and 30 normal cervical tissue samples." (PMID 25114911, 2014). "In fact, metastasization of cervical adenocarcinoma or squamous cell carcinomas is more frequent in tumors expressing high levels of CXCR4 than tumors that express either low levels or are negative for CXCR4." (PMID 20049170, 2010). "A functional in vitro study using a human squamous carcinoma cell line corroborated with human pathological findings and revealed that snail increases the CXCR4 expression on tumor cells in the presence of TGF-β1 and the EMT process augments tumor cell migration through the CXCR4–SDF-1 axis." (PMID 29503810, 2018).
myocardial ischemia (23 papers, 2011 to 2025). A disorder of cardiac function caused by insufficient blood flow to the muscle tissue of the heart. "The CXCL12/CXCR4 axis attaches great importance to myocardial repair after myocardial ischemia/reperfusion injury." (PMID 36131165, 2023). "SDF-1α is markedly upregulated within 1 h of myocardial ischemia, resulting in a chemoattractant gradient for CXCR4 expressing leukocytes and stem cells." (PMID 30678240, 2019). "In bone marrow and heart, CXCR4-EGFP was predominantly expressed in CD45+/CD11b+ leukocytes which significantly increased after myocardial ischemia." (PMID 28550361, 2017). "For example, the CXCL12/CXCR4 axis exerts cardioprotective effects after myocardial ischemia by enhancing the incorporation of progenitor cells in the infarcted region and promoting survival of cardiomyocytes." (PMID 26347749, 2015). "In this study, we reported here for the first time that the expression of miR-150 was downregulated in BM MNCs in response to myocardial ischemia with simultaneous induction of CXCR4 protein expression." (PMID 22039399, 2011). "Additionally, CXCR4 is involved in angiogenesis and regulates the homing, mobilization, and survival of progenitor cells, linking it to myocardial ischemia and injury-induced restenosis." (PMID 40143163, 2025). "CXCR4 has also been reported to mediate leukocyte chemotaxis in specific inflammatory diseases, and a similar role in inflammatory cell recruitment has been suggested in myocardial ischemia." (PMID 40143163, 2025). "Interestingly, DPP-4 inhibition improves cardiac function and reduces myocardial ischemia through SDF-1a/CXCR4-mediated STAT3 signaling and exerts an antiapoptotic effect on HUVEC under hypoxic conditions." (PMID 35615279, 2022). "In addition, it will be the goal of further studies to test a potential prognostic and therapeutic value of CXCR4 molecular imaging and the value of chemokine imaging in more clinically relevant models like myocardial ischemia/reperfusion injury as well as other cardiac inflammatory conditions." (PMID 32676914, 2021). "In a myocardial ischemia-reperfusion model, the excessive activation of SDF-1/CXCR4 pathway maintains the mitochondrial membrane potential and membrane permeability of cardiomyocytes to resist oxidative stress damage." (PMID 32256608, 2020). "Other studies are consistent with CXCL12-CXCR4 cardioprotection during pre- and post-myocardial ischemia, which is prevented by AMD3100 or a CXCR4 inducible knockout in cardiac myocytes." (PMID 32766282, 2020). "Numerous studies have revealed that myocardial ischemia significantly upregulates CXCL12 which then exerts a protective effect through CXCL12/CXCR4 signaling on resident cardiomyocytes." (PMID 31385396, 2019). "CXCR4 and its ligand CXCL12 are expressed in cardiac myocytes and fibroblasts, and myocardial ischemia significantly upregulates CXCL12." (PMID 24966838, 2014). "In conclusion, recent data indicate that similarly as CXCR4, MIF plays a double-edged role in myocardial ischemia." (PMID 24966838, 2014). "However, when mice were treated with roxadustat in the presence of myocardial ischemia, we observed a significant increase in mRNA levels for CXCL12, CXCR4, and ACKR3." (PMID 38994928, 2024). "The activation of the CXCR4/CXCL12 axis was found to play an important role in angiogenesis as well as the homing and mobilization of progenitor cells; this then results in the development of CVDs, including myocardial ischemia and infarction." (PMID 36979628, 2023). "Also, CXCR4 can form receptor complexes with CD7430,61, and MIF/CD74 signaling has important cardioprotective activities in myocardial ischemia/reperfusion injury." (PMID 29581527, 2018). "This indicates a double-edged role of CXCR4 in myocardial ischemia, which has also been described for MIF, as discussed in detail in recent reviews, and warns for a careful evaluation of effects of CXCR4 antagonists in clinical trials." (PMID 26347749, 2015).
myocardial ischemia (continued). "Furthermore, our data reveal that the increased CD133+ co-localize with CXCR-4+ and SDF-1α + cells in the area of myocardial ischemia." (PMID 22558265, 2012). "Using diabetic db/db mice subjected to myocardial ischemia, the present study investigates whether overexpression of Ang-1 promotes recruitment of hematopoietic progenitor cells into ischemic sites and whether this leads to attenuation of myocardial ischemic injury through SDF-1α/CXCR-4 signaling." (PMID 22558265, 2012).
asthma (22 papers, 2009 to 2025). "This study supports the clinical development of CXCR4 antagonists to address various diseases associated with CXCR4, including asthma and atopic dermatitis." (PMID 39070795, 2024). "CXCR4 controls immature B lymphocyte egress from the bone marrow and is implicated in the lung-homing of endothelial progenitor cells in experimental asthma." (PMID 27513955, 2016). "CXCL12/CXCR4 signaling was remarkedly up-regulated in asthma, predominantly bridging the interaction between fibroblasts and immune cell populations." (PMID 38317239, 2024). "This indicated that CXCL12/CXCR4 axis serves as a pivotal signaling pathway for fibroblast communication with immune cells that contributes to the pathogenesis of asthma." (PMID 38317239, 2024). "Another study using single-cell RNA-sequencing found that CXCR4 signaling in subsets of CD8+ T cells and monocyte clusters was associated with exacerbation in patients with asthma." (PMID 36733482, 2023). "Advanced derivatives of the Endogenous Peptide Inhibitor of CXCR4 (EPI-X4) have shown therapeutic efficacy upon topical administration in animal models of asthma and dermatitis." (PMID 36499357, 2022). "Of these, CXCR4, was found to be essential for fibrocyte recruitment in asthma, whereas its ligand CXCL12 was reported to be highly expressed in ESCC tissues." (PMID 35941662, 2022). "Platelets also express certain types of chemokine receptors (CCR3, CCR4, CXCR4) of pertinence to pulmonary cellular recruitment during asthma, although the physiological significance of these observations has not yet been fully elucidated." (PMID 33556295, 2021). "Cytokine-mediated regulation of CXCL12 has been demonstrated in eosinophils and lung epithelial cells; the effects of CXCL12/CXCR4 axis showed a contribution to the inflammatory response in a murine model of asthma." (PMID 24024210, 2013). "The natural fragment of serum albumin, EPI-X4, has been identified as an endogenous peptide antagonist and inverse agonist of CXCR4, and novel CXCR4 antagonists developed on the basis of this feature can be used in the treatment of atopic dermatitis, asthma, and other CXCR4-related diseases." (PMID 39026682, 2024). "Furthermore, our data showed that metformin suppressed the systematic expressions of VEGF, SDF-1 and CXCR4 in the plasma, thus mitigating neovascularization and inflammatory exudate in asthma." (PMID 35153777, 2022). "In asthma, MIF induces CCl2, CXCR2, and CXCR4 expression through the ERK / MAPK / P38 / Rho A GTPase pathway." (PMID 37422662, 2023). "The pro-inflammatory chemokine ligand 12 (CXCL12) binds to CXCR4 and has previously been shown to recruit numerous cell types such as lymphocytes, monocytes, and eosinophils into the lung airway fluid (BALF) of asthma patients." (PMID 32759853, 2020). "An up-regulation of CXCR4 and CXCL12 was reported in inflammatory diseases, such as rheumatoid arthritis, multiple sclerosis, nephritis and asthma." (PMID 22511975, 2012). "CXCR4 is also involved in Th2 cell migration into the lungs and treatment of allergic mice with selective CXCR4 inhibitors significantly reduces AHR and inflammatory responses, supporting the further development of CXCR4 antagonists for asthma treatment." (PMID 21867534, 2011). "Furthermore, CXCR4 was reported to decrease airway responsiveness and inflammation by reducing the levels of IL-4, IL-5, and IL-13 in the BALF in OVA-induced asthma." (PMID 34118928, 2021). "Accumulating evidence also suggests that CXCL12/CXCR4 signaling plays an important role in shaping the microenvironment, mediating allergic airway inflammation (such as retaining neutrophils at inflammatory sites) and promoting airway remodeling (e.g., induction of EMT) in asthma." (PMID 38317239, 2024). "However, the eosinophil population was not preponderantly impacted by the blockade of the CXCL12/CXCR4 axis, unlike in asthma and AESGF." (PMID 22511975, 2012).
bone tumor (22 papers, 2009 to 2025). "As such, it has been shown that the HIF-1α–VEGF–CXCR4 axis is a key driver in primary bone cancers and many of its effects can be prevented with the CXCR4 inhibitor AMD3100." (PMID 29098360, 2018). "The present study aimed to investigate the effects of miR-338 on morphine tolerance through the targeting of CXC chemokine receptor-4 (CXCR4) in a rat model of bone cancer pain (BCP)." (PMID 28108674, 2017). "Here we show that inhibition of CXCR4 with plerixafor is effective against bone tumor growth when given initially during tumor implantation." (PMID 27809841, 2016). "In this study, we investigated the specific cellular mechanisms of CXCL12/CXCR4 chemokine signaling in the development and maintenance of bone cancer pain after tumor cell implantation (TCI)." (PMID 24735601, 2014). "Taken together, these results demonstrate that CXCL12/CXCR4 signaling contributed to the development and maintenance of bone cancer pain via sensitizing neurons and activating astrocytes and microglia." (PMID 24735601, 2014). "Herein, we utilized DU145-HA-Akt1 overexpressing cells to specifically determine the contribution of Akt1 without perturbing the lipid/protein phosphatase functions of PTEN in CXCR4 expression and downstream signaling in bone tumor growth." (PMID 23902739, 2013). "In an analysis of Ewing sarcoma, another bone cancer, CXCR4 correlated with metastases, and CXCR4 in combination with CXCR7 were shown to be prognostic indicators for patient survival." (PMID 22518090, 2012). "CXCL12/CXCR4 signaling pathway activates sensitized neurons, astrocytes and microglia through mitogen-activated protein kinase (MAPK), promotes the release of inflammatory factors, such as IL(interleukin) and TNF, and causes persistent bone cancer pain." (PMID 39654896, 2024). "This find indicated that CXCL12/CXCR4 signaling may be making major contributions to nociceptive signal processing by mediating glial-neuronal and glial-glial communication on bone cancer state." (PMID 24735601, 2014). "Our previous data demonstrate that CXCR4 overexpression in the PTEN-null cell line PC-3 enhanced bone tumor growth in a SCID-human model; these tumors have activated Akt signaling, demonstrating the Akt signaling downstream of CXCR4 contributing to bone tumor growth." (PMID 23902739, 2013). "In addition, we recently found that epidermal growth factor receptor family members are activated downstream of CXCL12/CXCR4 signaling, providing proliferative signals in bone tumor growth." (PMID 23902739, 2013). "CXCR4 overexpression enhances bone tumor growth and osteolysis." (PMID 19508713, 2009). "However, whether CXCL12/CXCR4 signals contribute to pain hypersensitivity in the state of bone cancer is still largely unexplored." (PMID 39641645, 2024). "In addition, IHC analysis of lung, brain, and bone tumors revealed inhibition of CXCR4 expression." (PMID 30564115, 2018). "In the present study, we therefore reinvestigated the CXCR4-blocking principle for OS treatment in the human 143B OS cell line-derived intratibial xenograft model in SCID mice that closely mimics the human disease with metastasis from the primary bone tumor to the lung." (PMID 24390633, 2014). "However, it remains largely unknown whether the CXCL12/CXCR4 signaling contributes to pain hypersensitivity in a bone cancer state." (PMID 24735601, 2014). "The CXCR4 and its ligand CXCL12 are known to regulate the trafficking of various immune suppressive cells to the bone tumor microenvironment, thus contributing to the disease progression and therapy resistance." (PMID 37996444, 2023). "CXCR4 expression is also enhanced in bone tumors, suggesting that CXCL12/CXCR4 signaling contributing to bone tumor growth in Akt1 transfected DU145 cells." (PMID 23902739, 2013). "Furthermore, the hypoxic microenvironment in the bone tumour microenvironment (TME) involves HIF-1α and CXCR4 pathways." (PMID 41315643, 2025).